PEX3 (peroxisomal biogenesis factor 3)
Description:
Involved in peroxisome biosynthesis and integrity. Assembles membrane vesicles before the matrix proteins are translocated. As a docking factor for PEX19, is necessary for the import of peroxisomal membrane proteins in the peroxisomes.
Synonyms: PBD10A; PBD10B; TRG18
Tractability: Antibody: UniProt predicts a signal peptide or a membrane-spanning region. PROTAC: ubiquitination databases record sites on it; its protein half-life has been measured.
Gene: Protein-coding gene on chromosome 6 (143,450,805 to 143,490,616, forward strand). Ensembl gene ENSG00000034693.
Subcellular location: Peroxisome membrane
Subcellular location (Human Protein Atlas): Nucleoplasm; Peroxisomes
Pathways (Reactome):
Protein localization: Class I peroxisomal membrane protein import
Transport of small molecules: ABC transporters in lipid homeostasis
Gene Ontology:
Molecular function: lipid binding; protein binding; protein-macromolecule adaptor activity
Biological process: peroxisome organization; protein import into peroxisome membrane
Cellular component: endoplasmic reticulum; membrane; peroxisomal membrane; peroxisome; protein-containing complex; protein-lipid complex
Genetic constraint (gnomAD): Loss-of-function variants: 6 observed, 12.18 expected, observed/expected ratio (o/e) 0.49, 90% interval 0.27 to 0.97. The upper end of that interval is the gene's LOEUF score, 0.97, which puts it in group 4 of 6, group 1 being the genes least tolerant of losing a copy. Missense variants: 101 observed, 133.93 expected, observed/expected ratio (o/e) 0.75, 90% interval 0.64 to 0.89. Synonymous variants: 52 observed, 50.71 expected, observed/expected ratio (o/e) 1.03, 90% interval 0.82 to 1.29.
Gene-disease validity (ClinGen):
ClinGen rates the evidence that PEX3 causes each of these diseases.
peroxisome biogenesis disorder (autosomal recessive): Definitive.
Homologues: Orthologues: chimpanzee PEX3 (99% identical), macaque PEX3 (99% identical), dog PEX3 (97% identical), rabbit PEX3 (96% identical), guinea pig PEX3 (94% identical), mouse Pex3 (94% identical), pig PEX3 (91% identical), rat Pex3 (89% identical).